MYD88 (MYD88 innate immune signal transduction adaptor)
Diseases named in the same sentence as MYD88 in open-access papers (continued):
Sharing a sentence is not in itself a finding about the gene and the disease.
Sepsis (continued). "MYD88s is increased during sepsis and is thought to ensure robust termination of MYD88 dependent inflammation." (PMID 34017329, 2021). "Gene co-expression analysis across the 124 sepsis cohorts showed that IL6 gene expression was directly correlated to MYD88 (r = 0.26, p = 0.004) and NFKB1 (r = 0.19, p = 0.039) transcript levels." (PMID 34183713, 2021). "In this study, significant upregulation of MYD88 was identified in neonates with sepsis relative to uninfected controls." (PMID 34183713, 2021). "This was consistent with the MDSC expression of TLR5 and in agreement with the requirement of MyD88 for MDSC expansion during polymicrobial sepsis." (PMID 34208904, 2021). "In a murine model of LPS TLR4 activation-induced sepsis, signaling through the downstream adaptors MYD88 and TRIF result in permanent alterations to the HSC transcriptional programs." (PMID 34356379, 2021). "The occurrence of sepsis is related to the TLR4/MyD88 signaling pathway, which activates the secretion of cytokines associated with cardiac dysfunction in adult mammalian heart and in mice." (PMID 32423469, 2020). "Withdrawal or blocking of S100A8/A9 terminated the activation of the MyD88-dependent gene program and came along with an increased inflammatory response toward microbial stimuli in vitro and in vivo in experimental sepsis models." (PMID 32425933, 2020). "In the present study, we examined the role of TICAM2 (TRAM), which is an adaptor protein necessary for the recruitment of TRIF in the MyD88-independent pathway, in neutrophil exhaustion related to sepsis." (PMID 32873853, 2020). "Along similar lines, genipin and artesunate have also been shown to protect against sepsis by mitigating TLR4 activation through MyD88 downregulation." (PMID 33139717, 2020). "We also found that in comparison to the untreated sepsis group, narciclasine treatment reduced the protein expression of MyD88, IRAK-1 and TRAF-6 in the livers of septic neonatal rats." (PMID 32076015, 2020). "Overall, these data suggest that sepsis and lethal secondary septicemic plague develop more rapidly in Myd88−/− mice." (PMID 30642901, 2019). "miRNA-150 predicts survival in patients with sepsis, operating through MyD88 regulation, NFκB signaling, and toll-like receptor pathways." (PMID 30619110, 2018). "In this study we identified that rSj-Cys owns a therapeutic effect on CLP-induced sepsis through downregulating the TLR adaptor-transducer MyD88 pathway." (PMID 28482922, 2017). "The adaptor MyD88, which converges signals from multiple TLR, has also been implicated in generation of MDSC during polymicrobial sepsis." (PMID 29354120, 2017). "TLR-4 appears dispensable for sepsis-induced suppression of T cells thereby indicating that IL-1, which binds IL-1R upstream of MyD88, conditions MDSC differentiation." (PMID 29354120, 2017). "Here, we used a conditional gene targeting approach to specifically address the role of MyD88 in endothelial cells during polymicrobial sepsis." (PMID 26790027, 2016). "In order to evaluate the potential role of endothelial cells in CNS manifestations of sepsis, we chose to abrogate MyD88-dependent signaling in endothelial cells." (PMID 26790027, 2016). "Since the generationof IL-6 and TNF-α is highly relevant to LPS/TLR4/MyD88/MAPK/NF-κB signal pathway in sepsis, therefore, we verified the effect of dexmedetomidine on these signal molecules in CLP-induced septic rats." (PMID 25929655, 2015). "Since TLR4/MyD88/MAPK/NF-κB signal pathway plays a critical role in regulating the generation of inflammatory cytokines in endotoxemia or sepsis." (PMID 25929655, 2015). "Further, sepsis-induced expression of MYD88 was suppressed in animals treated with Mito-Vit-E, suggesting a mtROS-dependent signaling response." (PMID 26448624, 2015). "By contrast, we showed that MyD88-dependent signaling is crucial for the establishment of the local inflammatory response during CLP-induced sepsis." (PMID 25084278, 2014).
Sepsis (continued). "Here, we evaluated the role of Nod1, Nod2 and MyD88-dependent signaling in the chemokine production and neutrophil recruitment to the infectious site during sepsis induced by cecal ligation and puncture (CLP) in C57Bl/6 mice." (PMID 25084278, 2014). "In the context of sepsis, research efforts have been directed toward finding a mechanism to inhibit MyD88 and NF-κB and limit the excessive inflammation triggered by TLR." (PMID 25054155, 2014). "Together, these data therefore indicate that MyD88-dependent signaling is essential for the recognition of pathogens and triggering of the immune response in polymicrobial sepsis." (PMID 25084278, 2014). "By contrast, the establishment of the local inflammatory response, which leads to the control of infection in polymicrobial sepsis, is triggered by MyD88-dependent signaling." (PMID 25084278, 2014). "A recent study demonstrated that mice with selective expression of MyD88 in myeloid cells displayed enhanced hepatocellular injury during abdominal sepsis induced by cecal ligation and puncture." (PMID 25254554, 2014). "Initially, we observed that there was an up-regulation of TLR2, TLR4 and MyD88 in the WT mice that were subjected to sepsis." (PMID 22655058, 2012). "In the kidneys of knockout mice with sepsis, especially the MyD88 knockout mice, we found decreased expression of IL17, KC, iNOS, and MPO activity." (PMID 22655058, 2012). "C57BL/6 TLR2−/−, TLR4−/− and MyD88−/− male mice were subjected to sepsis by cecal ligation and puncture (CLP)." (PMID 22655058, 2012). "The results presented suggest that during sepsis AMs from diabetic rats over-express SOCS-1 which inhibits the expression of MyD88, thus preventing TLR-mediated signal transduction, NFkB activation and therefore the transcription of inflammatory genes." (PMID 23024779, 2012). "Fourteen tag single nucleotide polymorphisms (tagSNPs) in MyD88, IRAK1, IRAK4 and TRAF6 were genotyped in samples of sepsis-induced ALI (n = 272) and sepsis alone patients (n = 276), and tested for association in this case-control collection." (PMID 22901274, 2012). "Previous studies with MyD88−/− mice showed improved renal function of these animals after sepsis and also decreased serum levels of TNF compared with controls." (PMID 22655058, 2012). "Five genes, namely TLR2, TLR4, TLR9, MyD88 and TOLLIP, were investigated for their association with sepsis susceptibility by a tag single nucleotide polymorphism (SNP) strategy." (PMID 21219635, 2011). "The accumulation of MDSCs was dependent on MyD88 expression, as Gr1+CD11b+ cell recruitment to the spleen was inhibited during sepsis in MyD88-/- mice." (PMID 21966467, 2011). "Using the CLP model or a similar model, studies have established the critical role of MyD88 signaling in the pathogenesis of polymicrobial sepsis." (PMID 21977329, 2011). "On par with this concept, TLR2 or MyD88 KO mice have been demonstrated to be resistant to sepsis, indicating that TLR2 mediated signaling is playing an important role in the survival of bacterial pathogens." (PMID 21124939, 2010). "A NALB/c inbred male mice was studied as in vivo model of sepsis and observed that luteolin was found to have a role in inhibition of phagocytosis of macrophages, downregulation in expression of myeloid differentiation factor 88 (MyD88) and TLR4." (PMID 39830909, 2025). "DEX could attenuate AKI through KDM5A inhibition in sepsis, transcription and protein levels of genes such as TLR4, MYD88, MTA1, PTGS2, CASP3 associated with NF-κB signaling pathway were all compromising after treated with DEX." (PMID 40989844, 2025). "Therefore, calycosin can attenuate sepsis-induced acute lung injury by inhibiting the HMGB1/MyD88/NF-κB pathway and NLRP3 inflammasome activation." (PMID 41463300, 2025). "MyD88 has been proposed as a therapeutic target in sepsis-induced AKI." (PMID 40869248, 2025).
Sepsis (continued). "Therapeutically, enhancing Cbl activity could represent a strategy to treat MyD88-driven pathologies (e.g., sepsis and autoimmune disorders), while its conditional activation mechanism minimizes the risk of immunosuppression." (PMID 41562051, 2025). "Therefore, the TLR2/MyD88 signaling pathway can serve as an essential marker for the severity of sepsis and treatment efficacy." (PMID 38066526, 2023). "Thus, it can be concluded that MAF as a treatment reduces the inflammatory responses in vitro and in vivo by inhibiting the TLR4/ MyD88/NF‐κB pathway, and corrects intestinal flora imbalance during sepsis to some degree." (PMID 38455195, 2023). "In the study, mimics miR-22 could remarkably downregulate the LPS-induced increased TLR4, TLR2, MyD88, and p-NF-κB p65 protein expression, which indicated that miR-22 may alleviate sepsis-induced AKI by targeting HMGB1/TLR4/NF-κB signaling pathway." (PMID 35960478, 2023). "In addition, glycyrrhizin, the active component of traditional Chinese medicine, reduces neutrophil NETs formation in sepsis by inhibiting the activation of the HMGB1/TLR9/MyD88 (myeloid differentiation primary response 88) pathway." (PMID 36891309, 2023). "The expression of TLR-2/MyD88 in tissues was measured by western blot to determine whether TLR-2/MyD88 is involved in the sepsis-induced inflammatory signaling pathway." (PMID 38066526, 2023). "However, TLR4 agonists can significantly increase the expression of TLR4/MyD88/NF-κB signalling, thus reversing the protective effect of ulinastatin on sepsis." (PMID 38102579, 2023). "Also, TLRs is an upstream regulator of MyD88 and NF-kB which both involved in sepsis lung injury 6,7." (PMID 35637949, 2022). "TLR4-mediated MyD88/NF-κB signaling way is the key pathway in sepsis pathophysiology." (PMID 35722155, 2022). "This article aims to elucidate the mechanisms underlying the CASP-model sepsis by analyzing real-world GEO data (GSE24327_A, B and C) generated from mice spleen 12 hours after a CASP-surgery in septic MyD88-deficient and wildtype mice, compared with untreated wildtype mice." (PMID 35774781, 2022). "LNT regulates sepsis via the TLR4/MyD88 signaling pathway, according to previous research." (PMID 35669119, 2022). "Besides, in other sepsis-induced organ (lung, kidney, and liver) injury models, inhibition of MyD88 can improve the damage by reducing inflammation." (PMID 35571255, 2022). "To determine whether the HMGB1/TLR2/MyD88 signaling pathway is involved in the therapeutic effect of Ts-AES on sepsis-induced ALI, we evaluated protein and mRNA expression levels of HMGB1, TLR2 and MyD88 in lung tissue 12 h after CLP surgery." (PMID 33842398, 2021). "In the current study, gene expression analysis in 88 sepsis cohorts who survived, and 36 deceased neonates revealed a significant upregulation of MYD88 in expired cases (median = 3.81, IQR = 3.2–4.5) compared to alive ones (median = 3.27, IQR = 2.3–3.6), p = 0.007." (PMID 34183713, 2021). "Signaling through the adaptor protein MYD88 (an essential transducer for IL-1B and Toll-like receptor pathways) and the subsequent IFN-I stimulation has been implicated in conditioning of MDSC differentiation during sepsis." (PMID 34721400, 2021). "We addressed this by knocking out the toll receptor adapter protein, Myd88, only in skeletal muscle fibers (skmMyd88KO), and followed male and female mice at 6 and 12 h after peritoneal injection of cecal slurry (CS), a model of polymicrobial sepsis." (PMID 33795743, 2021). "In light of the present findings, the development and validation of new approaches for neonatal sepsis treatment are recommended, such as the potential use of TLR-pathway antagonists/inhibitors to limit the TLRs association with MyD88 preferentially and reduces the NFKB1 activity and/or IL68,39–41." (PMID 34183713, 2021).
Sepsis (continued). "Upregulated TLR4 and Myeloid Differentiation Primary Response 88 (MYD88) protein were demonstrated along with progranulin activation in our RT-qPCR-confirmed molecular network of the early antimicrobial response to sepsis." (PMID 34476621, 2021). "Taken together, our results demonstrated that GSS might be a promising candidate for sepsis‐induced ALI via its regulating effects on Myd88/NF‐κB/BCL‐2 signalling in lung ECs." (PMID 31756053, 2020). "Thus, CX43 in SPM is responsible for LPS-induced ATP release in peritoneal sepsis in a MyD88/TRIF dependent manner." (PMID 30735126, 2019). "Nuclear factor-κB signaling is one additional pathway that has been shown to be important for endothelial inflammation during sepsis and may be activated downstream of MyD88-dependent or through MyD88-independent mechanisms." (PMID 26790027, 2016). "We next examined whether sepsis alters the expression of TLR9 and related response factors, such as myeloid differentiation primary response protein MYD88 and IL-1R-associated kinase–4 (IRAK4)." (PMID 26448624, 2015). "Altogether, these data show that Nod1, Nod2 and Rip2 are not required for local chemokine production and neutrophil recruitment during CLP-induced sepsis, and they reinforce the importance of MyD88-dependent signaling for initiation of a protective host response." (PMID 25084278, 2014). "Even, the intensity of the infecting stimuli does not seem to be the explanation because we observed that MyD88-deficient mice had higher and faster mortality when undertaken to non-severe, moderate and severe sepsis." (PMID 25084278, 2014). "We found that neutrophil recruitment was markedly reduced in MyD88-deficient mice 6 and 24 h after non-severe sepsis induction." (PMID 25084278, 2014). "In this study, TsES reduced MyD88 and NF-κB expression during sepsis." (PMID 25054155, 2014). "Studies using mice in which Myd88 is deleted specifically in respiratory epithelium are warranted to establish the role of epithelial MyD88 in host defense against Klebsiella pneumonia derived sepsis." (PMID 25254554, 2014). "Corroborating the reduced systemic IL-6 levels, we also observed a reduction in neutrophil accumulation into the lungs of MyD88-deficient mice 6 and 24 h after non-severe sepsis induced by CLP." (PMID 25084278, 2014). "Due to the low plasma levels of IL-6 24 h after non-severe sepsis induction, we were not able to find significant difference between WT and MyD88-deficient mice." (PMID 25084278, 2014). "As expected, increased bacterial load in the peritoneal cavities and blood of MyD88-deficient mice were observed after non-severe sepsis induction." (PMID 25084278, 2014). "We demonstrate that myeloid, but nor endothelial cell MyD88 is important for host defense during pneumonia derived sepsis caused by Klebsiella." (PMID 25254554, 2014). "By contrast, we demonstrated that MyD88-dependent signaling is crucial for sepsis because the removal of this molecule completely abrogated the induction of a local chemotactic response, culminating in a higher susceptibility to CLP-induced sepsis." (PMID 25084278, 2014). "MyD88(−/−) mice subjected to sepsis had higher survival rate compared to the wild mice with sepsis." (PMID 25054155, 2014). "We demonstrate that MyD88 in myeloid cells, but not in endothelial cells, is important for host defense during pneumonia derived sepsis caused by Klebsiella pneumoniae." (PMID 25254554, 2014). "Given its effects on MyD88 and NF-κB, TsES might be a suitable novel therapeutic tool for treating sepsis." (PMID 25054155, 2014). "Some agents that inhibit MyD88 expression can ameliorate murine polymicrobial sepsis." (PMID 25054155, 2014). "Myeloid or endothelial cell MyD88 deficiency did not impact on lung pathology or distant organ injury during late stage sepsis, while LysM-Myd88−/− mice demonstrated a strongly attenuated inflammatory response in the airways early after infection." (PMID 25254554, 2014).
Sepsis (continued). "Because we showed that Nod1/Nod2 signaling was not indispensable for the production of chemokines and neutrophil recruitment to the infection site during polymicrobial sepsis, we investigated the importance of MyD88, the main adaptor protein of the TLR family, in these events." (PMID 25084278, 2014). "By inhibiting both MyD88 and NF-κB activity, TsES treatment may lead to fewer inflammatory factors during sepsis." (PMID 25054155, 2014). "Next, we also observed that MyD88-deficient mice had a reduction in IL-6 in the plasma 6 h after non-severe sepsis induction." (PMID 25084278, 2014). "However, the beneficial or deleterious role of the adaptor protein MyD88, recruited by these TLRs, to the outcome of polymicrobial sepsis still remains controversial." (PMID 25084278, 2014). "A therapeutic strategy for defeating sepsis by misleading MyD88 was proposed." (PMID 23940812, 2013). "Thus, we showed that the innate immunity receptors TLR2 and TLR4 and the adapter protein MyD88 are important in the development of AKI secondary to sepsis." (PMID 22655058, 2012). "It is known that LPS induces NFκB activation in a MyD88-dependent manner during sepsis and that the expression of this adaptor protein is negatively regulated by SOCS-1 so we then investigated the MyD88 and SOCS-1 (Suppressor of Cytokine Signalling) expression in the septic animals." (PMID 23024779, 2012). "To test this hypothesis, we conducted a case-control study using tag SNP approach to investigate the association of variants in MyD88, IRAK1, IRAK4 and TRAF6 with susceptibility and outcome of sepsis-induced ALI in Chinese Han population." (PMID 22901274, 2012). "The aim of this study was to investigate the role of TLR2, TLR4 and MyD88 in sepsis-induced AKI." (PMID 22655058, 2012). "Our results also indicated that tag SNPs of TLR2, TLR4, TLR9, and MyD88 did not represent major risk factors for sepsis development." (PMID 21219635, 2011). "They demonstrate that MyD88 signaling is the dominant determinant in mediating inflammation, cardiac dysfunction, and mortality, whereas Trif signaling plays no major role, in the development of cardiac dysfunction and mortality in severe polymicrobial sepsis." (PMID 21977329, 2011). "No haplotypes in TLR2, TRL4, TLR9, and MyD88 were associated with sepsis risk in this study (data not shown)." (PMID 21219635, 2011). "To test this hypothesis, we conducted a case control study using a tag SNP approach to investigate the association of variants in TLR2, TLR4, TLR9, MyD88, and TOLLIP with susceptibility to sepsis in the Chinese Han population." (PMID 21219635, 2011). "However, in a CLP model with a low grade of severity of peritoneal polymicrobial sepsis, MyD88−/− mice had worse survival compared with WT mice despite significantly attenuated systemic inflammation and reduced lymphocyte apoptosis in these mice." (PMID 21977329, 2011). "However, the induction of IRAK-M mRNA after CLP was nearly completely abolished in MyD88−/− mice, indicating the requirement for MyD88 in sepsis-induced expression of IRAK-M." (PMID 20585389, 2010). "Therefore, sepsis inflammation could be effectively counteracted by luteolin due to its role in inhibition of PPAR‐γ/STAT/MyD88 pathway (Miao, Li, and Li 2018)." (PMID 39830909, 2025). "In addition, the regulation of sepsis may be correlated with TLR4/MyD88/NF-κB signaling and alterations to the intestinal flora." (PMID 35722155, 2022). "Therefore, our results imply that TLR4/MyD88/NF-κB signaling may take part in the effect of EA at ST36 against sepsis." (PMID 35722155, 2022). "NFKBIA gene was iterated in 9 out of the 10 top pathways, MYD88 gene was enriched in 3 pathways, and IRAK4 was the only gene located on chromosome X. Their diagnostic accuracy was compared to IL6, which is used in our hospital protocol as a gold standard test for inflammatory reaction in sepsis." (PMID 34183713, 2021).